RNLS (renalase, FAD dependent amine oxidase)
Description:
Catalyzes the oxidation of the less abundant 1,2-dihydro-beta-NAD(P) and 1,6-dihydro-beta-NAD(P) to form beta-NAD(P)(+). The enzyme hormone is secreted by the kidney, and circulates in blood and modulates cardiac function and systemic blood pressure. Lowers blood pressure in vivo by decreasing cardiac contractility and heart rate and preventing a compensatory increase in peripheral vascular tone, suggesting a causal link to the increased plasma catecholamine and heightened cardiovascular risk. High concentrations of catecholamines activate plasma renalase and promotes its secretion and synthesis.
Synonyms: C10orf59; FLJ11218; renalase
Tractability: Small molecule: a structure with a bound ligand is known; it has a high-quality binding pocket. Antibody: UniProt places it where antibodies can reach, with high confidence; its Gene Ontology location is reachable by antibodies, with high confidence; UniProt predicts a signal peptide or a membrane-spanning region.
Gene: Protein-coding gene on chromosome 10 (88,273,864 to 88,584,530, reverse strand). Ensembl gene ENSG00000184719.
Subcellular location: Secreted
Pathways (Reactome):
Metabolism: Nicotinate metabolism
Gene Ontology:
Molecular function: epinephrine binding; monoamine oxidase activity; NADH binding; oxidoreductase activity, acting on NAD(P)H; protein binding; oxidoreductase activity
Biological process: negative regulation of blood pressure; negative regulation of heart rate; response to catecholamine; response to epinephrine; response to ischemia; response to salt
Cellular component: extracellular region
Genetic constraint (gnomAD): Loss-of-function variants: 31 observed, 34.69 expected, observed/expected ratio (o/e) 0.89, 90% interval 0.67 to 1.21. The upper end of that interval is the gene's LOEUF score, 1.21, which puts it in group 5 of 6, group 1 being the genes least tolerant of losing a copy. Missense variants: 384 observed, 409.34 expected, observed/expected ratio (o/e) 0.94, 90% interval 0.86 to 1.02. Synonymous variants: 144 observed, 150.85 expected, observed/expected ratio (o/e) 0.95, 90% interval 0.83 to 1.1.
Homologues: Orthologues: chimpanzee RNLS (99% identical), macaque RNLS (95% identical), pig RNLS (86% identical), rabbit RNLS (86% identical), dog RNLS (75% identical), rat Rnls (72% identical), mouse Rnls (71% identical), zebrafish rnls (60% identical), tropical clawed frog rnls (58% identical).
Diseases named in the same sentence as RNLS in open-access papers:
RNLS is named in the same sentence as 32 diseases in open-access papers, as found by Europe PMC text mining. Sharing a sentence is not in itself a finding about the gene and the disease. The quoted sentences say what the papers report.
Hypertension (6 papers, 2012 to 2024). The presence of chronic increased pressure in the systemic arterial system. "The RNLS gene Asp37Glu missense polymorphism (rs2296545) has been associated with hypertension, cardiac hypertrophy and dysfunction, and stroke." (PMID 34156537, 2021). "Recent studies delineate a possible role of this enzyme in blood pressure (BP) maintenance and cardiac protection and two single nucleotide polymorphisms, RNLS rs2576178 A > G and rs2296545 C > G have been associated with hypertension." (PMID 22812913, 2012). "Furthermore, numerous single nucleotide polymorphisms (SNPs) reside within the RNLS gene with certain ones - rs792205, rs10887800, rs2296545, rs2576178, and rs1935582 - reportedly being linked with elevated levels of blood pressure or risk of hypertension." (PMID 39232213, 2024). "Regarding the role of renalase in hypertension and ischemic-related diseases and the being rare published report about the effects of renalase polymorphisms on stroke; in the current study, we investigated the probable effects of RNLS rs2576178 and rs10887800 polymorphisms on IS in young patients." (PMID 34603559, 2021).
chronic kidney disease (3 papers, 2017 to 2024). Impairment of the renal function secondary to chronic kidney damage persisting for three or more months. "RNLS deficiency is associated with end-stage renal disease and hypertension." (PMID 35322081, 2022).
diabetes (2 papers, 2021 to 2024). "Therefore, in the present case–control study, we aimed to assess the potential involvement of the RNLS gene rs2296545 polymorphism in microvascular complications of type 2 diabetes mellitus." (PMID 34156537, 2021).
autoimmune disease (1 paper, 2025). A disorder resulting from loss of function or tissue destruction of an organ or multiple organs, arising from humoral or cellular immune responses of the individual to their own tissue constituents. "All but four out of 26 red group signals (PRF1, CTRB2, MEG3 and RNLS) were associated with other autoimmune diseases found in the Open Targets Genetics portal." (PMID 39749473, 2025).
chronic pancreatitis (1 paper, 2021). A chronic inflammatory process causing damage and fibrosis of the pancreatic parenchyma. "In a chronic pancreatitis case (associated CTRC mutation) we observed co-localization of RNLS and αSMA, suggesting that RNLS may be present in stellate cells." (PMID 34587190, 2021).
left ventricular hypertrophy (1 paper, 2022). Enlargement of the LEFT VENTRICLE of the heart. "Knockout of RNLS aggravated cardiac remodeling in CKD, while RNLS cardiac-specific overexpression significantly reduced left ventricular hypertrophy and cardiac fibrosis induced by CKD." (PMID 36588579, 2022).
melanoma (1 paper, 2024). A malignant, usually aggressive tumor composed of atypical, neoplastic melanocytes. "Additionally, inhibitory antibodies raised against the RP220 signaling module of the RNLS protein reduce RNLS tumor expression and tumor growth in murine melanoma models when given as single agents." (PMID 39102218, 2024).
myocardial ischemia (1 paper, 2022). A disorder of cardiac function caused by insufficient blood flow to the muscle tissue of the heart. "RNLS deficiency in cardiac tissue exacerbates myocardial damage after myocardial ischemia and reperfusion, and exogenous RNLS protein protects against this damage by reducing cell necrosis and apoptosis." (PMID 35898283, 2022).
pancreatic ductal adenocarcinoma (1 paper, 2016). An infiltrating adenocarcinoma that arises from the epithelial cells of the pancreas. "RNLS gene expression was increased in pancreatic ductal adenocarcinoma cell (PDAC) lines with KRAS2 mutations (MiaPaCa2 and Panc1) compared to those with wild type KRAS2, such as BxPC3." (PMID 26972355, 2016).
stomach adenocarcinoma (1 paper, 2024). "CpGs located in the same CGI of TMEM101 (n = 4) and RNLS (n = 2) were hypermethylated in uterine corpus endometrial carcinoma and stomach adenocarcinoma, respectively." (PMID 38336771, 2024).
cancer (4 papers, 2016 to 2025). A tumor composed of atypical neoplastic, often pleomorphic cells that invade other tissues. "Together, these studies provided compelling evidence of key regulatory roles for RNLS as a prosurvival factor and modulatory of inflammatory responses in preclinical models of acute tissue injury as well as in cancer." (PMID 34440775, 2021). "Our findings identify RNLS as a secreted protein that can promote the survival and growth of PDACs, and provide a framework to further investigate the use therapies that inhibit RNLS for the treatment of cancer." (PMID 26972355, 2016). "Our data indicate that the inhibition of RNLS signaling will tilt the balance toward cancer cell death." (PMID 26972355, 2016). "The role of renalase (RNLS) in cancer progression and ferroptosis regulation remains unclear." (PMID 40799250, 2025).
tumor (4 papers, 2016 to 2025). "These in vivo data conclusively demonstrate RNLS’s oncogenic role through STAT3-dependent modulation of tumor growth and redox balance." (PMID 40799250, 2025). "We believe that the results obtained from 4 different cell lines, and 2 tumor models provide support for the hypothesis that inhibition of RNLS signaling may be cytotoxic to other tumors." (PMID 26972355, 2016).
infection (3 papers, 2018 to 2023). The state of being infected such as from the introduction of a foreign agent such as serum, vaccine, antigenic substance or organism. "Fluorescence observation and qPCR quantification of PR1 mRNA indicated that both SADR1 and RNLs (ADR1s in particular) regulate defense at the borders of infection sites." (PMID 36893276, 2023).
cardiovascular diseases (1 paper, 2021). "Further studies are needed to explore the possible role of RNLS as a new therapeutic target in the prevention and treatment of CKD and cardiovascular diseases." (PMID 33800219, 2021).
renal diseases (1 paper, 2022). "Renalase (RNLS) is a newly discovered protein secreted by the kidney and was found beneficial in many renal diseases." (PMID 36588579, 2022).
RNLS also shares sentences with these, for which no sentence is quoted: cardiac hypertrophy (2 papers); aortic stenosis (1); Autoimmunity (1); coronary artery disorder (1); end-stage renal disease (1); gastric cancer (1); metabolic disease (1); Obesity (1); oral cancer (1); Oral leukoplakia (1); pancreatic cancer (1); prostate carcinoma (1); Stroke (1); type 1 diabetes (1); type 2 diabetes mellitus (1); uterine cancer (1); uterine corpus endometrial carcinoma (1).